TMEM236 (transmembrane protein 236)
Synonyms: FAM23A; FAM23B; bA16O1.2; bA162I21.2
Tractability: Antibody: UniProt predicts a signal peptide or a membrane-spanning region.
Gene: Protein-coding gene on chromosome 10 (17,752,201 to 17,800,868, forward strand). Ensembl gene ENSG00000148483.
Subcellular location: Membrane
Gene Ontology:
Molecular function: protein binding
Cellular component: membrane
Genetic constraint (gnomAD): Loss-of-function variants: 12 observed, 17.16 expected, observed/expected ratio (o/e) 0.7, 90% interval 0.45 to 1.13. The upper end of that interval is the gene's LOEUF score, 1.13, which puts it in group 4 of 6, group 1 being the genes least tolerant of losing a copy. Missense variants: 464 observed, 451.07 expected, observed/expected ratio (o/e) 1.03, 90% interval 0.95 to 1.11. Synonymous variants: 182 observed, 178.65 expected, observed/expected ratio (o/e) 1.02, 90% interval 0.9 to 1.15.
Homologues: Orthologues: chimpanzee TMEM236 (99% identical), macaque TMEM236 (93% identical), rabbit TMEM236 (77% identical), rat Tmem236 (75% identical), mouse Tmem236 (74% identical), pig TMEM236 (72% identical), dog TMEM236 (71% identical), guinea pig TMEM236 (69% identical), zebrafish tmem236 (37% identical).
Diseases named in the same sentence as TMEM236 in open-access papers:
TMEM236 is named in the same sentence as 5 diseases in open-access papers, as found by Europe PMC text mining. Sharing a sentence is not in itself a finding about the gene and the disease. The quoted sentences say what the papers report.
colorectal cancer (3 papers, 2021 to 2026). A primary or metastatic malignant neoplasm that affects the colon or rectum. "TMEM236 has the potential to be a potential novel diagnostic biomarker for colorectal cancer." (PMID 35962453, 2022). "Past studies have understood the TMEM236 highly expressed in pancreatic α cells that secrete glucagon, elevating blood glucose, also considered to be a potential novel diagnostic biomarker for colorectal cancer, due to significantly downregulated in colorectal tumors." (PMID 41544045, 2026).
colorectal tumors (3 papers, 2021 to 2026). "TMEM236 is a new gene significantly downregulated in colorectal tumors." (PMID 36405735, 2022). "Most importantly, TMEM236 is a novel gene that is significantly downregulated in colorectal tumors." (PMID 34253750, 2021).
Insulin resistance (1 paper, 2026). Increased resistance towards insulin, that is, diminished effectiveness of insulin in reducing blood glucose levels. "There has been little research on whether TMEM236 is involved in growth regulation, only speculating that up-regulation of TMEM236 may be linked to insulin resistance." (PMID 41544045, 2026).
tumor (2 papers, 2021 to 2022). "TMEM236 differentially expresses itself in the CRC dataset where its expression is downregulated in tumor samples as compared to normal samples." (PMID 34253750, 2021). "Moreover, the expression of prognostic genes (LINC00643, TMEM236, and hsa-miR-135a-5p) displayed differences between GC tissues and adjacent non-tumor tissues." (PMID 36405735, 2022). "Normal gastric tissues had moderate TMEM236 IHC staining, whereas tumor tissues had weak staining." (PMID 36405735, 2022). "The difference in the expression level between normal and tumor samples is huge for TMEM236." (PMID 34253750, 2021).
TMEM236 also shares sentences with these, for which no sentence is quoted: brain disorder (1 paper).